GDF15 (growth differentiation factor 15)
Diseases named in the same sentence as GDF15 in open-access papers (continued):
Sharing a sentence is not in itself a finding about the gene and the disease.
Anorexia (continued). "Interestingly, our here uncovered GDF15‐dependent diurnal anorexia resembles an endogenous mimic of time‐restricted feeding response." (PMID 32026535, 2020). "It is interesting to note that increased GDF15 has been measured in the circulation of human cancer subjects and, recently an NTS → CGRPPBN → CeA/ovBNST axis has been implicated in mediating the anorexia associated with cancer models in mice." (PMID 32723474, 2020). "Interestingly, an earlier study from the same group has shown that switching to a fasting metabolism (which should be a consequence of GDF-15/GFRAL/RET-induced anorexia) can be life-saving in LPS- or Listeria-induced experimental sepsis." (PMID 32508832, 2020). "Together, these and recently published data suggest that GDF15 is probably not a natural satiety factor, but exerts a pathophysiological action to cause anorexia." (PMID 32723474, 2020). "Functionally, GDF-15 is a main culprit for anorexia in cancer patients." (PMID 32508832, 2020). "Modulating GDF-15 in anorexia and cachexia, where GDF-15 is the prime regulator, might thus be therapeutically beneficial." (PMID 32508832, 2020). "Thus, we propose that the primary target for GDF15 is a distinct population of GFRAL/CCK neurons which span the AP/NTS to engage well-characterised circuitry involved in anorexia and conditioned aversion." (PMID 32723474, 2020). "The authors concluded that the anorexia observed with GDF15 administration was driven by nausea; however, it should be noted that a lower dose of 0.1 mg/kg did not illicit emesis in the musk shrew but resulted in comparable weight loss to the animals treated with the emetic dose." (PMID 32310257, 2020). "Consequently, this should stimulate translational research on GDF15 as a therapeutic target for the treatment of anorexia and hypermetabolism during mitochondrial disorders." (PMID 32026535, 2020). "Conversely, researchers from the Novartis Institute for Biomedical Research found that anorexia and muscle loss, as complications in cancer, are mainly caused by increased levels of GDF-11, with GDF-15 being upregulated in response to supraphysiologic administration of GDF-11." (PMID 32508832, 2020). "Thus, Mic-1/Gdf15 is involved in the physiological regulation of appetite and energy storage, a process that becomes subverted in some disease states leading to anorexia/cachexia." (PMID 28081177, 2017). "Weight loss and anorexia could also be induced acutely in mice by administration of recombinant MIC-1/GDF15, an effect mediated via the direct action of MIC-1/GDF15 in areas of the brain that regulate appetite." (PMID 22514681, 2012). "The unique action of GDF15 on GFRAL at area postrema/nucleus tractus solitarii (AP/NTS) neurons is suggested to activate neurons in the parabrachial nucleus (PBN)-central amygdala circuit to mediate food and taste aversion, GDF15 driven anorexia and weight loss." (PMID 38474863, 2024). "Children with cancer are particularly vulnerable to chemotherapy-induced nausea, vomiting, and anorexia, and elevations of GDF15 may predict patients with higher rates of gastrointestinal symptoms, muscle loss, and weight loss, as has been seen in adult cancers such as pancreatic cancer." (PMID 38146512, 2023). "This is in line with mounting evidence that GDF15 could cause food aversion and malaise as an endocrine signal of nutritional stress and the recent finding that central delivery of GDF15 into rats and shrews induced behaviors indicative of nausea and emesis preceding the onset of anorexia." (PMID 33464381, 2021). "GDF15 may mediate its anorexia effects by acting on these receptors." (PMID 33344478, 2020). "However, no conclusive data are available in humans on the role of GDF-15 in cancer-associated anorexia." (PMID 33396237, 2020).
Anorexia (continued). "However, elevated GDF15 may contribute to the anorexia/cachexia syndrome observed in chronic heart failure—so-called cardiac cachexia—which is an important determinant of patient well-being and clinical outcome." (PMID 32310257, 2020). "Hence, the persistent GDF15 elevation in critically ill patients may mediate gastro-intestinal intolerance of enteral feeding and may contribute to their anorexia." (PMID 32928255, 2020). "Lastly, since we can block GDF15- or cisplatin-induced anorexia by neutralising the GFRAL receptor with a selective monoclonal antibody, we suggest that the anorectic responses to disease and, potentially, their therapeutic treatment may be mediated by this distinct signalling pathway." (PMID 32723474, 2020). "GDF15 is secreted by a range of tissues, including the liver, inguinal WAT and BAT, and can contribute to sickness‐induced anorexia independently of TNFα, via direct signalling in the hindbrain." (PMID 39428707, 2025). "Growth differentiation factor 15 (GDF15) is a member of the TGF‐β family and produces anorexia by directly acting on the feeding center of the brainstem." (PMID 36105371, 2022). "A prior report proposed the minimal clinical difference in numerical rating scale for anorexia as 1.5 points, and the median MDASI-J score in our study was 3 points higher in the high-GDF-15 group than in the low-GDF-15 group." (PMID 34638326, 2021). "Patients with MADD with anorexia had significantly higher GDF15 levels (8412pg/mL) than those without anorexia (5513 pg/mL)." (PMID 40181460, 2025). "In this study, we show that anorexia is not responsive to anti-GDF-15 therapy despite increased levels in the serum." (PMID 35941104, 2022). "Ablation of Gdf15 in UCP-tg mice prevented their day time restricted anorexia without affecting the physical activity pattern." (PMID 33464381, 2021). "Moreover, recent data demonstrated that mitochondrial stress-induced GDF15 promotes a day-time restricted anorexia and systemic metabolic remodeling as shown in UCP1-transgenic mice, where both FGF21 and GDF15 are induced as myomitokines." (PMID 33464381, 2021). "Together with the fact that no anorexia was observed, these results suggest that GDF11 induces a healthy, GDF15‐independent weight loss in aged mice." (PMID 31637864, 2020). "Our comparative analysis demonstrated significantly higher GDF15 levels in patients with MADD with anorexia than in those without anorexia, suggesting that elevated GDF15 may contribute to the anorexia observed in these patients." (PMID 40181460, 2025). "Thus, a low plasma concentration of GDF15 would be expected in patients with anorexia, rather than an elevated level." (PMID 36545337, 2022). "Noteworthy, gastrointestinal cancer patients, who were characterized by a higher grade of anorexia (considering their lower FAACT score), showed higher GDF-15 serum levels compared to lung cancer patients that may be, at least in part, related to the heterogeneity of the gastrointestinal group." (PMID 33396237, 2020). "In addition to inducing anorexia in disease, recent data suggested that MIC-1/GDF15 might also play a role in the physiological regulation of appetite, body weight and fat mass." (PMID 24971956, 2014). "Thus, SPIOMET increased the GDF15 levels in adolescents with PCOS from low-normal (0.2–0.4 ng/mL) into high-normal range (0.8–1.2 ng/mL); it reduced liver steatosis, insulin resistance and low-grade inflammation, and raised adiponectinaemia, without causing anorexia or a loss of body weight." (PMID 33782413, 2021). "Interestingly, the GDF-15 serum levels were significantly higher in patients with cancer compared to our control group and, more importantly, anorexic cancer patients showed higher GDF-15 concentrations compared to those without anorexia." (PMID 33396237, 2020).
prostate carcinoma (102 papers, 2007 to 2025). A carcinoma that arises from epithelial cells of the prostate gland. "In contrast, elevated levels of NAG-1/GDF15 have been associated with cancer progression, recurrence, and poor survival outcomes in prostate cancer." (PMID 40316530, 2025). "For instance, NAG-1/GDF15 has been implicated in the progression of prostate cancer, as evidenced by its role in promoting bone metastasis in prostate cancer cells." (PMID 40316530, 2025). "Similar associations are observed in colorectal, pancreatic, and prostate cancer, where GDF15 contributes to metastasis and therapy resistance." (PMID 40868185, 2025). "For prostate cancer, several studies have shown an association between elevated serum GDF‐15 levels and bone metastasis." (PMID 41380167, 2025). "Here, prostate cancer cells caused osteocytes to produce GDF15, which in turn promoted prostate cancer cell proliferation, migration and invasion." (PMID 36642986, 2023). "In murine prostate cancer, GDF15 overexpression was associated with increased CD8+ T cell numbers and a reduced proportion of CD8+PD-1+ T cells." (PMID 36472770, 2023). "For prostate cancer, the inverse association of risk with GDF-15 appeared more pronounced for high-grade than low-grade disease." (PMID 34935094, 2022). "Novel observations from our study are the increased risk of lung cancer, and the reduced risk of prostate cancer, among individuals who had higher blood levels of GDF-15." (PMID 34935094, 2022). "The inverse association between GDF-15 and prostate cancer risk was more pronounced for high-grade disease, with a borderline significant heterogeneity (p-heterogeneity = 0.05)." (PMID 34935094, 2022). "On the other hand, having simultaneously high levels of NT-proBNP and low levels of GDF-15 is associated with a 83% increase in prostate cancer risk." (PMID 34935094, 2022). "The subcutaneous implantation of GDF15-overexpressing prostate cancer cell led to weight loss and reduced food intake in mice, whereas GDF15 antibody administration rescued the mice from weight loss especially by preventing lean mass wasting." (PMID 36230682, 2022). "In the same report the authors demonstrated that serum GDF15 levels were positively associated with the amount of weight loss in a longitudinal study of patients with advanced prostate cancer." (PMID 32310257, 2020). "A disease-modifying effect of GDF-15 is further supported by findings that a polymorphism in the GDF15 gene (H6D) affects both tumor risk and prognosis in colorectal and in prostate cancer (HR: 0.83 or 0.85 from two different studies)." (PMID 32508832, 2020). "This is strongly supported by epidemiological data, which shows that GDF-15 is a risk factor for metastasis and death from prostate cancer." (PMID 32508832, 2020). "For example, increased local concentrations of extracellular matrix associated MIC-1/GDF15 in prostate cancer biopsies were associated with reduced risk of disease progression, especially in the subgroup with early cancer and with Gleason grade of 6 or less." (PMID 25695521, 2015). "Xenograft of MIC-1/GDF15 expressing human prostate cancer cells into mice leads to loss of fat and lean body mass, and this appears to be directly due to decreased food intake." (PMID 22514681, 2012). "However, some studies include that of Rybicki et al62, who observed lower GDF-15 expression in male NHB participants in a benign biopsy prostate cancer risk study." (PMID 39989973, 2025). "Additionally, elevated serum levels of NAG-1/GDF15 in prostate cancer patients are associated with reduced survival rates." (PMID 40316530, 2025). "Furthermore, elevated levels of GDF15 associated with prostate cancer facilitated bone metastasis and bone turnover, while the deletion of GDF15 in this context inhibited osteoblast differentiation and mineralization." (PMID 38392243, 2024).
prostate carcinoma (continued). "While all of them were independently associated with CVD risk, we observed for the first time that combining NT-proBNP and HbA1C associates strongly with breast cancer risk, GDF-15 and NT-proBNP with prostate cancer risk, and GDF-15 and HbA1C with lung cancer risk." (PMID 34935094, 2022). "Interestingly, levels of GDF-15 showed a significant inverse association with risk of prostate cancer." (PMID 34935094, 2022). "An inverse association was observed for GDF-15 and prostate cancer risk." (PMID 34935094, 2022). "Moreover, lower GDF15 levels were associated with shorter time to distant metastasis and to prostate cancer-specific death." (PMID 31539407, 2019). "However, the same study showed that in prostate cancer samples, lower GDF15 expression is associated with higher Gleason pattern and pathologic stage and increased risk of relapse after surgery." (PMID 31539407, 2019). "In addition, in patients diagnosed with prostate cancer, breast cancer, lung cancer and colorectal cancer higher levels of GDF-15 were associated with the occurrence of bone metastases." (PMID 30646851, 2019). "Since low GDF15 expression is associated with more aggressive prostate cancer and worse clinical outcome, induction of GDF15 may be a viable approach to treat advanced prostate cancer and prevent prostate cancer progression." (PMID 31539407, 2019). "Among the identified TDFs, GDF-15 is highly expressed in various malignant cancers and is associated with the proliferation, metastasis and prognosis of colon cancer, ovarian cancer, oral squamous cell carcinoma, melanoma and prostate cancer." (PMID 24236027, 2013). "Likewise, GDF15 has been associated with the progression of diseaseto metastasis and has also been proposed as a prostate cancer biomarker." (PMID 20500816, 2010). "GDF15 expression was found to be elevated in tumours and in serum samples from patients suffering from and various cancer types, including pancreatic, colorectal and prostate cancer and melanoma and may cause resistance to chemotherapeutics 15,25–28." (PMID 25823874, 2015). "Prostate cancer is characterized by high levels of IL-1β, IL-18, IL-6, and MIC-1/GDF-15 that are clinically relevant for this association with the risk of carcinoma and the prognosis of established cancer." (PMID 41560727, 2025). "In prostate cancer (PCa), GDF15 outperforms prostate-specific antigen (PSA) in distinguishing PCa from benign prostate hyperplasia and healthy controls." (PMID 40868185, 2025). "Prostate cancer patients with high NAG-1/GDF15 exhibit poor prognosis, while colorectal cancer patients show the opposite trend." (PMID 40316530, 2025). "On the other hand, our data suggest that pro-NAG-1/GDF15 overexpression in prostate cancer cells exerts anticancer activity." (PMID 40316530, 2025). "Previous research has shown that pro-NAG-1/GDF15 binds to the extracellular matrix (ECM) in prostate cancer cells." (PMID 40316530, 2025). "Recent evidence has also demonstrated the expression of GFRAL in prostate cancer cells, suggesting a potential role of GDF15 in disease pathogenesis." (PMID 40868185, 2025). "Within this publication, the prostate cancer tumor microenvironment was shown to have a significantly higher expression of growth differentiation factor 15 (GDF15) as compared to the healthy prostate microenvironment." (PMID 37222464, 2023). "Osteocytes produce GDF15, and the knockdown of this gene in bone diminished the proliferation of prostate cancer cells injected into the tibiae of mice." (PMID 37174109, 2023). "Prostate cancer can promote the vicious cycle of bone metastasis progression by inducing osteocytes to secrete GDF15 that stimulates prostate cancer growth and invasion." (PMID 37206921, 2023). "Growth differentiation factor 15 (GDF15) has been reported to play an important role in cancer and is secreted and involved in the progression of various cancers, including ovarian cancer, prostate cancer, and thyroid cancer." (PMID 36769245, 2023).
prostate carcinoma (continued). "To date, proprotein convertase, subtilisin/kexin-type (PCSK) 3, 5, and 6 have been recognized as proteases able to cleave pro-GDF15 in in vitro and in vivo studies on cardiomyocytes, heart, and prostate cancer." (PMID 36698863, 2022). "Together, our study indicates that EGFR pathway is inhibited by GDF15 in untreated and short-term AR inhibitor treated LNCaP prostate cancer cells." (PMID 35853851, 2022). "Osteocyte-derived GDF15 enhances prostate cancer cell proliferation and invasion by promoting the interaction between osteocytes and prostate cancer cells." (PMID 35280749, 2022). "The first evidence of the possible correlation between weight and GDF15 has been obtained by studying individuals with advanced prostate cancer: in these subjects, high circulating GDF15 levels correlated with weight loss." (PMID 36176473, 2022). "More recently, prostate cancer–derived GDF15 was found to increase the osteoclastogenic potential of osteoblasts, which secrete RANKL and CCL2 to promote bone resorption." (PMID 35994202, 2022). "It was reported that EGR1 expression was required for the osteocyte-derived GDF15-mediated induction of in vitro prostate cancer cell proliferation, migration and invasion." (PMID 34681812, 2021). "In prostate cancer PC-3 cells, induced expression of GDF15 reduced cell proliferation, formation of soft agar clone, and xenograft tumor growth." (PMID 34208589, 2021). "1,25(OH)2D3–induced upregulation of growth differentiation factor 15 (GDF15) mRNA level has been observed in prostate cancer LNCaP cells." (PMID 34208589, 2021). "As an essential component of more complex marker panels, GDF-15 is a potential marker to aid in the discrimination between prostate cancer and benign hyperplasia." (PMID 32508832, 2020). "In previous studies, GDF15 expression was elevated in many cancers such as breast, cervical, colorectal, ovarian, pancreatic, and prostate cancers as well as glioblastomas, melanomas, and oral squamous cell carcinomas." (PMID 33086658, 2020). "The C57BL/6 transgenic TRAMP prostate cancer prone mice were bred with mice that were immunodeficient and/or systemically overexpressed GDF15." (PMID 32502202, 2020). "Its anorectic actions were first identified using GDF15 overexpressing human prostate cancer xenografts in nude BALB/c mice." (PMID 32310257, 2020). "We have been studying the role of GDF15 in the spontaneous development of prostate cancer (PCa) in C57BL/6 background TRAMP mice in which we have genetically manipulated GDF15 expression." (PMID 32502202, 2020). "In prostate cancer, where GDF-15 expression was also found in tumor-associated fibroblasts, GDF-15 was positively associated with tumor cell proliferation, cancer progression and anchorage-independent growth." (PMID 32508832, 2020). "In the TRAMP transgenic model of spontaneous prostate cancer, transgene-mediated overexpression of GDF-15 reduced the growth of the primary tumor." (PMID 32508832, 2020). "The interaction between prostate cancer cells and osteocytes induces the osteocytic production and release growth-derived factor 15 (GDF15) promoting prostate cancer cell proliferation, migration, and invasion of prostate cell in the bone." (PMID 33162934, 2020). "Xenografts formed in mice from a prostate cancer cell line expressing a proGDF15 mutant that cannot be processed exhibited marked upregulation of extracellular matrix (ECM)-bound GDF15." (PMID 32310257, 2020). "In contrast, another study showed that overexpression of GDF15 led to an increase in the dissemination of prostate cancer cells." (PMID 33086658, 2020). "Circulating levels of GDF15 are raised in a range of human malignancies, including malignant glioma, pancreatic cancer, colorectal cancer, and prostate cancer." (PMID 32310257, 2020).